BST2 (bone marrow stromal cell antigen 2)
Diseases named in the same sentence as BST2 in open-access papers (continued):
Sharing a sentence is not in itself a finding about the gene and the disease.
HIV-1 infection (44 papers, 2009 to 2025). The type species of lentivirus and the etiologic agent of acquired immunodeficiency syndrome (AIDS). "Previous studies reported that BST-2 genetic variants or single nucleotide polymorphims (SNPs) have a preventative role during HIV-1 infection." (PMID 35081977, 2022). "Collectively, these data suggest that bst-2 genetic variants may have a preventative or modifying role in HIV-1 infection or disease progression." (PMID 35081977, 2022). "Here we show that expression levels of BST-2, a potent antiviral cellular protein are negatively associated with viral loads in an antiretroviral-naive cohort of women followed longitudinally from acute HIV-1 infection." (PMID 34025670, 2021). "The involvement of deubiquitinases (DUBs) in counteracting BST-2 ubiquitination and influencing its stability during HIV-1 infection remains inadequately explored." (PMID 40007014, 2025). "Briefly, BST2 restricts HIV-1 infection by “tethering” virions on the budding membrane thus restraining viral propagation." (PMID 39561185, 2024). "Here, we identify that IL-27 can produce opposing effects on HIV-1 replication in PBMCs and that the HIV-1 restriction factor BST-2/Tetherin is involved in both inhibitory and enhancing effects on HIV-1 infection induced by IL-27." (PMID 36602368, 2023). "Beyond its direct role in the restriction of viral dissemination, BST2 acts as a viral sensor by inducing NF-κB-dependent proinflammatory responses to HIV-1 infection." (PMID 37660915, 2023). "IL-27 favors HIV-1 infection when added 4 days later to infected cells and this effect involves BST-2/Tetherin." (PMID 36602368, 2023). "In HIV-1 infection, the ecto-domain of BST2 can restrict virus budding at the plasma membrane, while the hemITAM motif in the cytoplasmic tail of BST2 phosphorylated by Src-family kinases can activate NFκB signaling." (PMID 36232695, 2022). "Meanwhile, similar result was demonstrated in shUSP33 HeLa cells that BST2 degradation was enhanced during HIV-1 infection (lanes 2 and 4) and subsequently promoted HIV-1 infectivity." (PMID 34630422, 2021). "In a previous study we observed that cocaine significantly downregulated BST-2, a Type II transmembrane protein known to offer intrinsic resistance against HIV-1 infection." (PMID 34530855, 2021). "Our study also revealed that cocaine induced downregulation of BST-2 can alter biogenesis, cargo recruitment and release of EVs in immune cells during HIV-1 infection." (PMID 34530855, 2021). "In these mouse models, strong type I IFN responses and subsequent BST-2 upregulation were detected upon HIV-1 infection." (PMID 31213558, 2019). "This also directly correlated with the production of ISGs, as exemplified by tetherin/BST2, which was preferentially induced by HIV-1 infection in CD4 T cells and macrophages in peripheral circulation but was not induced in splenic CD4 T cells or macrophages." (PMID 30867315, 2019). "While all studies to date in chronic infection have used IFN-α2a, other IFN-α subtypes, as well as IFN-β, have been shown to be more potent at upregulating BST-2 and restricting HIV-1 infection." (PMID 31213558, 2019). "While BST-2 expression is upregulated upon HIV-1 infection by endogenous type I IFNs, a recent study revealed that basal BST-2 levels are sufficient to suppress HIV-1 replication." (PMID 31213558, 2019). "Tetherin or BST2 (bone marrow stromal cell antigen 2, also called CD317, HM1.24) is a type I and II interferon-induced transmembrane protein, first discovered as a cellular restriction factor against HIV-1 infection." (PMID 30126090, 2018). "It performs two distinct functions in HIV-1 infection: causing CD4 degradation in the endoplasmic reticulum and promoting viral particle release by counteracting BST-2." (PMID 26935098, 2016). "For the first time, we have identified a small molecule compound IMB-LA that inhibits HIV-1 infection by exposing HIV-1 to BST-2 restriction." (PMID 26669976, 2015).
HIV-1 infection (continued). "Theoretically, blocking the antagonist function of Vpu should expose HIV-1 to the potent restriction by BST-2 and therefore constitutes a new strategy to treat HIV-1 infection." (PMID 26669976, 2015). "Because BST2 is an interferon-stimulated gene, the BST2 upregulation can be triggered by type I interferon, which is induced by HIV-1 infection." (PMID 25807049, 2015). "Manipulating the function and potency of cellular restriction factors such as BST-2/tetherin to HIV-1 infection, has implications in the design of antiviral therapeutic strategies." (PMID 23311681, 2013). "As shown here, and as previously reported, BST-2/tetherin is expressed at low levels on DC from myeloid origin but its expression is increased after HIV-1 infection." (PMID 23311681, 2013). "The cellular transmembrane protein CD317/BST-2/HM1.24/Tetherin restricts HIV-1 infection by physically tethering mature virions to the surface of infected cells." (PMID 21310048, 2011). "BST2’s antiviral functions were first described in 2008 on HIV-1 infection." (PMID 39561185, 2024). "A previous study showed that BST-2 is upregulated during HIV-1 infection." (PMID 35081977, 2022). "Vpu is an HIV-1 accessory protein generated from Env/Vpu encoded bicistronic mRNA and localized in cytosolic and membrane regions of cells capable of being infected by HIV-1 and that regulate HIV-1 infection and transmission by downregulating BST-2, CD4 proteins levels, and immune evasion." (PMID 34452331, 2021). "Thus, in addition to its role in viral restriction, BST-2 acts as a sensor of HIV-1 infection leading to pro-inflammatory responses." (PMID 31426525, 2019). "Interestingly, administration of IFN-α during chronic HIV-1 infection was found to enhance BST-2 expression and tended to decrease HIV-1 replication (59, –, 61)." (PMID 31213558, 2019). "The antiviral host factor BST2 restricts viral egress of HIV-1 by tethering the virus to the cell and polymorphisms in BST2 and the regulatory sequences of BST2 are associated with the progression of HIV-1 infection." (PMID 28973976, 2017). "In this study, we demonstrate for the first time that a small molecule compound 2-thio-6-azauridine inhibits Vpu-induced BST-2 degradation, increases BST-2 level at the cell surface in the presence of Vpu and, as a result, inhibits wild type HIV-1 infection of BST-2-expressing cells." (PMID 26935098, 2016). "However, the research on Vif has finally lead to the identification of APOBEC3G, which opens up a new era in the research field of host restriction factors in HIV-1 infection followed by TRIM5α, Tetherin/BST-2, and SAMHD1." (PMID 23430691, 2013). "While cell culture studies have provided important insight into the mechanistic basis of Vpu-mediated BST2 antagonism and HIV-1 release, it is not clear how Vpu mutations that impair β-TrCP recruitment and inhibit Vpu-mediated BST2 degradation affect HIV-1 infection in vivo." (PMID 24195843, 2013). "Furthermore, it has been reported that polymorphisms in the promoter and 3‘ untranslated region of the bst2 gene may affect the clinical outcome of HIV-1 infection." (PMID 23937976, 2013). "At present, cause(s) of BST2 up regulation by HIV-1 infection in the absence of Vpu is not clear." (PMID 24195843, 2013). "Constitutively expressed ISGs regulated by U-ISGF3 included antiviral genes such as BST2, APOBEC3G, MX2 that remained elevated during chronic HIV-1 infection." (PMID 33064743, 2020). "In the context of HIV-1 infection, Vpu suppresses TLR7-mediated IFN-I production by pDCs through a mechanism that relies on the interaction of BST-2 on HIV-producing cells with ILT7 on pDCs." (PMID 31426525, 2019). "These include host restriction factors such as APOBEC3G, TRIM5α, Tetherin (also known as BST-2), SAMHD1, and MX2, which have been reported to restrict HIV-1 infection and replication." (PMID 30496280, 2018).
HIV-1 infection (continued). "The microarray analysis also showed that HIV-1 infection induced various IFN-stimulated genes (ISGs) including HIV-1 restriction factors such as MX2, APOBEC3G (A3G), BST2, and IFITMs in MDMs." (PMID 30496280, 2018). "To circumvent the caveats caused by the lower sensitivity of HRS depleted HEK 293T cells to HIV-1 infection, we analysed the outcome of HRS depletion in HeLa cells depleted for BST-2." (PMID 21304933, 2011). "Next, we investigated whether endogenous BST-2 mRNA expression levels in PBMCs translated to BST-2 protein expression levels on the surface of CD4+ T cells, the main target cells of HIV-1 infection in vivo." (PMID 35081977, 2022). "For example, in HeLa-CD4 cells expressing high level of BST2, Vpu deletion did not enhance HIV-1 infection in one-step assay (unpublished data)." (PMID 31027334, 2019). "Furthermore, like BST2, depletion of cell surface EWI-2 by HIV-1 infection was abrogated in the presence of reverse transcriptase inhibitors, and when cells were infected with Vpu-deficient HIV-1." (PMID 31757023, 2019). "Furthermore, HIV-1-infected THP1-CD4-sh-β-TrCP cells did not downregulate surface BST2 (compare dot plots j and k), which is usually reduced from the cell surface through a Vpu/β-TrCP-related mechanism following HIV-1 infection (compare dot plots d and e)." (PMID 41283654, 2025). "One key factor that could associate cortical AFs with the cell surface and appears to regulate late stages of the HIV-1 infection cycle is the interferon (IFN)-induced type II membrane glycoprotein tetherin, also known as bone marrow stromal cell antigen 2 (BST2), HM1.24 or CD317." (PMID 37685911, 2023). "Our observation that Vpu preferentially targets BST-2 over other TM proteins (NTB-A, PVR, and CD62L) upon IFN treatment raises the possibility that the polyfunctionality of Vpu could be reduced during acute HIV-1 infection." (PMID 31213558, 2019). "Moreover, cell surface expression of BST2 was not downregulated further upon HIV-1 infection in Rab7A knockdown cells (compare gate C2 to C1 on the upper 2nd panel)." (PMID 22072966, 2011). "Thus, although BST2 antagonism may not be absolutely required for HIV-1 infection in humans, counteraction of BST2 function may be required for CST of HIV-1 to macaques." (PMID 32477302, 2020). "It is possible that in vivo HIV-1 infection may up regulate BST2 levels in IFN dependent and independent manner and that the latter may reflect potential effects of other HIV-1 proteins such as Nef, which has been shown to up regulate BST2 levels on dendritic cells." (PMID 24195843, 2013). "We recently reported that during chronic, untreated HIV-1 infection, IFN-I inducible antiretroviral genes APOBEC3G, BST2 and MX2, as well as IFNβ, but not IFNα, were expressed to significantly higher levels when compared to HIV-1 uninfected individuals." (PMID 33064743, 2020). "Although it is not completely clear how IMB-LA blocks BST-2 degradation, IMB-LA inhibits HIV-1 infection only in cells that express BST-2." (PMID 26669976, 2015). "Immunofluorescence staining showed that, in control cells, HIV-1 infection (revealed by staining for Env) led to reduced BST-2 staining, compared to neighbouring non-infected cells, whereas BST-2 labelling was comparable in infected and non-infected cells when HRS was depleted." (PMID 21304933, 2011). "While still not fully elucidated, the inability to completely clear an HIV-1 infection could largely be due to accessory proteins, such as Vpu, that aid in immune system evasion through mechanisms such as the downmodulation of CD4, BST-2/Tetherin, and inhibitory effects on ADCC." (PMID 35458546, 2022).
breast cancer (37 papers, 2009 to 2025). A primary or metastatic malignant neoplasm involving the breast. "The overexpression of BST2 in breast cancer cells is associated with enhanced cell proliferation and inhibition of apoptosis." (PMID 36016386, 2022). "In the breast cancer model, we found upregulation of the membrane-associated factors, E-selectin, BST2, and HMMR, as well as the cytokine CCL7 only under mixture-culture conditions." (PMID 31963450, 2020). "In breast cancer cells, elevated levels of BST-2 have been associated with increased cancer cell migration, invasion, adhesion, and resistance to apoptosis/anoikis." (PMID 32155736, 2020). "Fluorescent gelatin degradation assay indicates that suppression of BST-2 significantly reduced the area of gelatin proteolysis by 4T1 breast cancer cells as indicated by the loss of fluorescent signal." (PMID 30514852, 2018). "This current study used pre-clinical and clinical data to provide evidence that BST-2 is directly linked to the aggressive phenotype and metastatic potential of breast cancer cells." (PMID 30514852, 2018). "Although BST-2 has been linked to breast cancer cell migration and invasion, in this study, we demonstrate that BST-2 overexpression is a requirement for enhanced migratory response in various cancer cells." (PMID 29299143, 2017). "To do this, we overexpressed well-characterized variants of human BST-2 in BST-2-suppressed breast cancer cell lines." (PMID 29299143, 2017). "There is now irrefutable evidence that overexpression of the innate immunity protein―BST-2, in breast cancer cells is implicated in tumor growth and progression." (PMID 29299143, 2017). "We show that BST-2 gene expression is inversely associated with the methylation status at specific CpG sites in primary breast cancer specimens and breast cancer cell lines." (PMID 25860442, 2015). "By using RNA interference, we show that loss of BST-2 enhances MMTV replication in cultured mammary tumor cells and in vivo." (PMID 22284121, 2012). "Mahauad-Fernandez’s research group reported that knockdown of BST2 inhibits mammary tumor growth and metastasis, both in vitro and in vivo, and high BST2 expression in breast tumors is positively associated with tumor size and aggressiveness as well as poor patient survival." (PMID 30655550, 2019). "The expression of bone marrow stromal protein 2 (BST2), which can be associated with the development of bone metastasis in human breast cancer, is significantly increased in bone metastatic breast cancer cell lines and tumor tissue compared with nonbone metastatic breast cancer cell lines." (PMID 25147739, 2014). "Based on the results of previous reports suggesting the association of galectins with tumor malignancy in breast cancer, renal cancer, thyroid cancer, and other cancers, antibody therapy aiming at blocking either BST2 or Gal-8/-9 could be an option for anti-cancer therapy." (PMID 36232695, 2022). "BST2 is more highly expressed in breast cancer cells derived from patients presenting bone metastasis than in human primary breast cancer cells." (PMID 35968507, 2022). "In our study, the continuous decrease observed in the levels of Bst2 and Irgm was also consistent with reports describing their role as survival promoters in breast cancer and melanoma cells." (PMID 36430209, 2022). "Mahauad Fernandez and Okeoma suggested that BST-2 targets breast cancer cells that are resistant to anoikis via the GRB2/ERK/BIM/Cas3 pathway." (PMID 35432482, 2022). "Several studies revealed that bone marrow stromal antigen-2 (BST-2) is overexpressed in breast cancer cells, leading to increased adhesion and invasion of these cells." (PMID 36476230, 2022). "BST-2 also plays key role in promoting oncogenic processes in many cancers, including breast cancer and its expression in these cancers is elevated relative to known cancer markers." (PMID 32872253, 2020).
breast cancer (continued). "BST-2 is a novel driver of cancer progression whose expression confers oncogenic properties to breast cancer cells." (PMID 32872253, 2020). "In breast cancer cells, BST-2 mediates cancer cell adhesion and anchorage-independent growth thereby promoting tumor cell survival through inhibition of anoikis." (PMID 31963450, 2020). "We have previously shown that overexpression of BST-2 in breast cancer cells promotes cancer cell adhesion and aggressiveness." (PMID 32872253, 2020). "This study provides the first evidence that a BST-2-based peptide (B18L) is a promising therapeutic agent for treatment of breast cancers, thus supporting further development." (PMID 32872253, 2020). "Based on these findings, we propose that CBX6 potentially plays a tumor suppressor role through repression of BST2 in breast cancer." (PMID 30655550, 2019). "The loss of BST-2 dimerization-mediated cell to cell/ECM interaction inhibits cancer cell clustering, induces anoikis in breast cancer cells through BST-2/GRB2/ERK/BIM/Cas3 pathway, and inhibits tumor growth and metastasis." (PMID 29523843, 2018). "For this purpose, we utilized the 4T1 breast cancer model in which BST-2 plays an important role in spontaneous metastasis to conduct experimental metastasis studies." (PMID 30514852, 2018). "Further, exogenous expression of BST-2 in the luminal A human breast cancer cell line MCF-7 confers migratory and invasive abilities to the cells." (PMID 30514852, 2018). "We further showed that the mechanism by which BST-2 dimerization promotes breast cancer involves a previously unreported BST-2/GRB2/ERK/BIM/Cas3 pathway." (PMID 29523843, 2018). "In breast tumors, the level of BST-2 is significantly higher when compared to notable markers of breast cancer, including estrogen receptor, progesterone receptor, HER2, or Myc6." (PMID 29523843, 2018). "The aim of this study was to evaluate the effect of a novel BST-2-based peptide—B49 on adhesion and growth of breast cancer cells." (PMID 29523843, 2018). "We previously reported that in breast cancer, BST-2 renders cancer cells resistance to anoikis through the GRB2/ERK/BIM/Cas3 pathway." (PMID 30514852, 2018). "Increased expression of BST-2 in breast cancer has been shown to mediate various facets of breast cancer progression including cell adhesion, anchorage-independent growth, survival, primary tumor growth, invasion, and metastasis." (PMID 30514852, 2018). "In our studies, we identified BST-2/GRB2/ERK/BIM/Cas3 as an important pathway in anoikis evasion by breast cancer cells." (PMID 28300825, 2017). "The number of BST-2-expressing (shCTL) breast cancer cells was higher in the wound area compared to BST-2-suppressed (shBST-2) cells within the same time." (PMID 29299143, 2017). "Previous studies have demonstrated that BST-2 regulates cellular machinery that mediates migration and invasion of epithelia-derived breast cancer cells." (PMID 29299143, 2017). "Evidently, BST-2 is present in circulating breast cancer cells, and levels are elevated in cells that circulate as clusters." (PMID 28300825, 2017). "We have identified the structural requirements for BST-2-regulated migration and invasion of breast cancer cells." (PMID 29299143, 2017). "The effect of BST-2 on cell migration is not limited to breast cancer cells because shRNA-mediated reduction of BST-2 level impairs the migratory potential of cells representative of other cancer types." (PMID 29299143, 2017). "Here, we confirm that silencing BST-2 expression in the aggressive triple negative murine breast cancer cells 4T1 impairs cell motility in a two-dimensional (2D) co-culture wound healing assay." (PMID 29299143, 2017). "Expression of the BST2 gene was upregulated in tamoxifen-resistant MCF-7 human breast-cancer cells, human mammary xenografts resistant to tamoxifen and in breast cancer patients with bone-marrow metastases." (PMID 28611294, 2017).